ARMC3 (armadillo repeat containing 3)
Description:
Essential for male fertility and sperm motility (By similarity). During spermatogenesis, promotes the autophagic degradation of excessive ribosomes, providing energy resources for mitochondria and thus ensuring sperm flagellar motility.
Synonyms: CT81; FLJ32827; VAC8; KU-CT-1
Tractability: No criterion of Open Targets' tractability assessment is met for any kind of drug.
Gene: Protein-coding gene on chromosome 10 (22,928,024 to 23,038,523, forward strand). Ensembl gene ENSG00000165309.
Gene Ontology:
Biological process: flagellated sperm motility; ribophagy; spermatid development
Cellular component: extracellular exosome
Genetic constraint (gnomAD): Loss-of-function variants: 57 observed, 78.11 expected, observed/expected ratio (o/e) 0.73, 90% interval 0.59 to 0.91. The upper end of that interval is the gene's LOEUF score, 0.91, which puts it in group 3 of 6, group 1 being the genes least tolerant of losing a copy. Missense variants: 878 observed, 1,017.1 expected, observed/expected ratio (o/e) 0.86, 90% interval 0.82 to 0.91. Synonymous variants: 313 observed, 355.2 expected, observed/expected ratio (o/e) 0.88, 90% interval 0.8 to 0.97.
Homologues: Orthologues: chimpanzee ARMC3 (99% identical), macaque ARMC3 (97% identical), pig ARMC3 (89% identical), dog ARMC3 (87% identical), rat Armc3 (84% identical), guinea pig ARMC3 (84% identical), mouse Armc3 (83% identical), tropical clawed frog armc3 (62% identical), zebrafish armc3 (49% identical). Paralogues in human: ANKAR (18% identical), JUP (16% identical), ODAD2 (16% identical), CTNNB1 (15% identical).
Diseases named in the same sentence as ARMC3 in open-access papers:
ARMC3 is named in the same sentence as 18 diseases in open-access papers, as found by Europe PMC text mining. Sharing a sentence is not in itself a finding about the gene and the disease. The quoted sentences say what the papers report.
male infertility (3 papers, 2021 to 2025). The inability of the male to effect fertilization of an ovum after a specified period of unprotected intercourse. "The expression of ARMC3 is significantly increased in highly active sperm, whereas the deletion of exon 11 of the ARMC3 gene may alter the reading frame, leading to premature termination of translation, which causes sperm defects and thus male infertility." (PMID 34912852, 2021). "A previous study demonstrated that ribosome removal was disrupted in the elongated spermatids of ARMC3 knockout mice, which led to ribosomal protein accumulation, immotile flagella, and complete male infertility." (PMID 39516485, 2024). "Moreover, it has been reported that the expression of ARMC3 is significantly increased in highly active sperm, whereas the deletion of exon 11 of the ARMC3 gene may alter the reading frame, leading to premature termination of translation, which causes sperm defects and thus male infertility." (PMID 34912852, 2021).
infertile (2 papers, 2016 to 2020). "Although these data point at a number of potential molecular targets only three causative mutations, resulting in male sub- or infertility in cattle have been determined in the FSHB, TMEM95, and ARMC3 gene hitherto." (PMID 31963602, 2020).
fertility disorder (1 paper, 2016). "In any case, it is recommended to survey sequence variants in ARMC3 in bulls with fertility disorders in cattle breeds other than Swedish Red." (PMID 26923438, 2016).
tumor (3 papers, 2022 to 2025). "Cd274 and Zbtb32 negatively regulate immunity, and S100a4, Rap1gap, Armc3, and Prkar2b promote tumor metastasis, This was consistent with the emergence of immunosuppression in the later stages of E. granulosus infection and with the hydatid cyst metastasis." (PMID 36569953, 2022). "While AASEs of tumor-related genes, such as ARMC3, TPM4, and TNFRSF12A had higher inclusion levels in G3." (PMID 35989380, 2022).
genetic disease (1 paper, 2022). "The paralogs of ARMC3 are involved in causing various genetic disease conditions in humans, e.g., ARMC2 (OMIM: 618424; 6q21) variants cause severe asthenoteratozoospermia in humans and mice." (PMID 36553564, 2022).
neurodevelopmental disorder (1 paper, 2022). A behavioral and cognitive disorder with onset during the developmental period that involves impaired or aberrant development of intellectual, motor, or social functions. "ARMC3 may lead to neurodevelopmental disorders, including stuttering in humans." (PMID 36553564, 2022).
ARMC3 also shares sentences with these, for which no sentence is quoted: cancer (2 papers); breast carcinoma (1); ciliopathies (1); colorectal cancer (1); cryptococcosis (1); esophageal squamous cell carcinoma (1); head and neck squamous cell carcinoma (1); Hypertension (1); infection (1); lung carcinoma (1); melanoma (1); multiple myeloma (1).